RNU2-24P (RNA, U2 small nuclear 24, pseudogene)
Gene: Small nuclear RNA gene on chromosome 10 (27,193,358 to 27,193,500, reverse strand). Ensembl gene ENSG00000252639.
Homologues: Orthologues: chimpanzee U2 (76% identical), rabbit U2 (52% identical). Paralogues in human: RNU2-41P (51% identical), RNU2-26P (49% identical), RNU2-57P (49% identical), RNU2-58P (49% identical), RNU2-60P (49% identical), RNU2-55P (47% identical), RNU2-72P (47% identical), RNU2-22P (46% identical), RNU2-43P (46% identical), RNU2-16P (45% identical), RNU2-69P (45% identical), RNU2-28P (45% identical), and 65 more.